EZH2 (enhancer of zeste 2 polycomb repressive complex 2 subunit)
Diseases named in the same sentence as EZH2 in open-access papers (continued):
Sharing a sentence is not in itself a finding about the gene and the disease.
bladder cancer (continued). "NSC745885 treatment down-regulated the EZH2 expression in eight cancer cell lines, including prostate, breast, kidney, and bladder cancers." (PMID 25431950, 2014). "Here we demonstrated that down-regulation of EZH2 in tumor tissues after neo-adjuvant chemotherapy correlated with good therapeutic response in advanced bladder cancer." (PMID 25431950, 2014). "The data in this study also demonstrate that the down-regulation of EZH2 expression also correlates with the therapeutic response to neo-adjuvant chemotherapy of patients with advanced bladder cancer." (PMID 25431950, 2014). "Four patients with good therapeutic response had significantly down-regulated EZH2 expression in bladder cancer tissues after neo-adjuvant chemotherapy." (PMID 25431950, 2014). "It has been previously shown to modulate the EZH2-mediated H3 K27 trimethylation of bladder cancer cells." (PMID 25431950, 2014). "Staining serial sections of tumor samples with EZH2 revealed that EZH2 was highly expressed in 12 bladder cancer tissues." (PMID 25431950, 2014). "Converse to frequent observations of decreased MHC II expression in tumors are observations of overexpression of EZH2 in diverse tumors types including prostate, breast and bladder cancers and links to enhanced tumor cell proliferation." (PMID 22563434, 2012). "Beyond these interactions, GAS5 directly modulates the activity of subsequent genetic targets, such as binding to the insulin receptor (IR) promoter to regulate its expression and promoting apoptosis in bladder cancer cells by downregulating the transcription of enhancer of zeste homolog 2 (EZH2)." (PMID 40563948, 2025). "EZH2 levels increase in many cancers, including aggressive bladder carcinomas." (PMID 40918525, 2025). "In the context of lung adenocarcinoma, CAMK2A has been demonstrated to support tumor-initiating cells by upregulating SOX2 through the phosphorylation of EZH2, indicating a potential mechanism by which it may also affect bladder cancer." (PMID 40893939, 2025). "Experimental results suggest that EZH2 may promote the proliferation and migration of bladder cancer cells through the STAT3 pathway, highlighting its potential role in bladder cancer progression." (PMID 40635786, 2025). "Notably, recent studies demonstrated that EZH2-mediated repression plays a direct role in immune escape in bladder cancer." (PMID 40918525, 2025). "In summary, bladder cancer’s alterations in histone modification pathways–whether via mutation (KDM6A, ARID1A, KMT2D) or overexpression (EZH2, HDACs) – are a central component of its biology and interact with aging." (PMID 40918525, 2025). "Cells with ARID1A deletion in bladder cancer are more sensitive to EZH2 inhibitors." (PMID 39779467, 2025). "However, even after surgery, serum EZH2 levels in bladder cancer patients remained notably higher when compared to those in healthy individuals." (PMID 38476362, 2024). "This indicates that serum EZH2 could be a novel biomarker for bladder cancer diagnosis and prognosis." (PMID 38476362, 2024). "The data showed that at an optimal cut-off value of 8.23 ng/ml, EZH2 levels could effectively distinguish bladder cancer patients from healthy individuals." (PMID 38476362, 2024). "Investigations in bladder cancer tissues revealed that miR-194-5p is frequently downregulated due to promoter hypermethylation, and a cisplatin treatment can epigenetically increase this hypermethylation mediated by EZH2." (PMID 38256203, 2024). "This indicates that serum EZH2 could be a meaningful biomarker for predicting the recurrence of bladder cancer." (PMID 38476362, 2024). "In addition, EZH2 is highly expressed in bladder cancer, while JAK2/STAT3 signalling pathway is abnormally activated." (PMID 38506082, 2024). "Additionally, studies have shown that inhibiting EZH2 activity can significantly suppress the proliferation and metastasis of bladder cancer cells." (PMID 38476362, 2024).
bladder cancer (continued). "Moreover, EZH2 levels in the serum of bladder cancer patients were significantly higher than those in healthy control individuals, and the median serum EZH2 levels were 36.23 ng/ml and 8.12 ng/ml, respectively." (PMID 38476362, 2024). "Specifically, EZH2 plays a crucial role in maintaining the low immunogenicity of bladder cancer cells by transcriptionally repressing cytokines and MHC class II antigen presentation genes, which leads to immune evasion and further shapes an immune-cold tumor microenvironment." (PMID 38036539, 2023). "Recently, Wu revealed BRD4 as a novel promising target for pharmacologic treatment against bladder cancer and reported that BRD4 regulates proliferation and apoptosis of bladder cancer cells by positively regulating EZH2 transcription through upregulation of c-MYC." (PMID 36733715, 2023). "Similarly, GAS5 has been demonstrated as a tumor suppressor role in bladder cancer via inhibiting EZH2 expression and augmenting apoptosis." (PMID 36685879, 2022). "Moreover, miR-200c regulated EZH2 through BMI-1 and E2F in breast, lung, prostate, bladder cancers and hepatocarcinoma." (PMID 36316365, 2022). "Another study reveals the role of SNHG1 in bladder cancer progression via regulating EZH2." (PMID 35236381, 2022). "EZH2 is also the target of tazemetostat, a small molecule inhibitor effective in treating follicular lymphoma and epithelioid sarcoma, suggesting a potential role for the drug in bladder cancer." (PMID 36192513, 2022). "The high expression of EZH2 may be one of the mechanisms of bladder cancer cells in acquiring radiation resistance." (PMID 36071871, 2022). "EZH2 is regarded as a potential therapeutic target for bladder cancer." (PMID 36428492, 2022). "Furthermore, GAS5 has been reported to promote apoptosis by suppressing EZH2 transcription via the recruitment of transcription factor E2F4 to EZH2 promoter in bladder cancer cells." (PMID 36685879, 2022). "Likewise, a study in bladder cancer has further verified the GAS5 role in promoting apoptosis through inhibiting EZH2 transcription similarly by recruiting transcription factor E2F4 to EZH2 promoter." (PMID 35736636, 2022). "Furthermore, ARID1A-mutated (herein referred to as ARID1Amut) bladder cancers expressed high levels of EZH2, consistent with previous findings that EZH2 expression is upregulated in bladder cancer." (PMID 35852858, 2022). "Furthermore, Foxp3-specific EZH2 inactivation led to enhanced production of pro-inflammatory cytokines as well as reduced tumor size in murine bladder cancer." (PMID 34737746, 2021). "H19 increased bladder cancer metastasis by binding to EZH2 and inhibiting E-cadherin expression." (PMID 33267897, 2020). "In TCGA database, we found EZH2 was up-regulated in bladder cancer tissues." (PMID 32047553, 2020). "In addition, lnc00518 knockdown was capable of downregulating EZH2 expression, indicating a presence of lnc00518/miRNA-101/EZH2 axis in the regulation of bladder cancer." (PMID 32047553, 2020). "Moreover, lncRNA GAS5 was reported to suppress enhancer of zeste homolog 2 (EZH2) transcription via recruiting E2F4 to EZH2 promoter to induce bladder cancer cell apoptosis." (PMID 32308561, 2020). "The LBCS/hnRNPK/EZH2 complex promotes chemoresistance in bladder cancer via silencing of SOX2." (PMID 33050646, 2020). "Overall, these findings suggest to us that NK cell-mediated tumor cell killing may be partially response for anti-tumor activity observed with EZH2 inhibition alone and in combination with cisplatin in bladder cancer xenografts in nude mice." (PMID 30692641, 2019). "Interestingly, previous publication reported that SPRY4-IT1 positively regulates posttranscriptional expression of EZH2 by sponging miR-101-3p in bladder cancer." (PMID 29642935, 2018).
bladder cancer (continued). "Our data do not support ARID1A-deficiency as predictive biomarker for EZH2-inhibitor treatment response in bladder cancer underlining the need for future bladder cancer-specific, drug screens for successfull discovery of ARID1A-deficiency-based targeted drugs." (PMID 30138427, 2018). "Given the importance of the FGF-2/KDM2B-EZH2/miR-101/EZH2 axis in bladder cancer, we hypothesize that there will be clinical utility to the therapeutic targeting of this pathway." (PMID 28515962, 2017). "We knocked down and overexpressed EZH2 in parallel groups of T24 bladder cancer cells, which were subsequently treated with the anticancer drugs, gemcitabine and cis-diamminedichloridoplatinum (II) (cisplatin, DDP), survival rates were assessed in vitro by performing a CD-DST." (PMID 28968986, 2017). "Another study showed that USP21 expression is upregulated in bladder tumors and suggested that USP21 could promote cancer growth and metastasis by inhibiting the ubiquitylation of EZH2 in bladder cancer cell lines." (PMID 28969054, 2017). "Recently, several studies have suggested that the enhancer of zeste homolog 2 (EZH2) could be a key potential factor in the development of drugs for targeted therapy in multiple tumors, including bladder cancer." (PMID 28968986, 2017). "For instance, lncRNAs SPRY4-IT1 could sponge miR-101-3p and consequently increase EZH2 expression to promote cellular proliferation and metastasis of bladder cancer cells." (PMID 29228631, 2017). "Studies have revealed that the sensitivity of GA-treated human bladder cancer cells to apoptosis triggered by methyl jasmonate is relevant to the down-regulation of enhancer of zeste homologue 2 (EZH2) level by the elevation in the expression of miR-101, which directly targets EZH2." (PMID 28052018, 2017). "In addition, the pRB-E2F pathway tightly regulates EZH2 expression that promotes bladder cancer development." (PMID 28410242, 2017). "Therefore, in this study, the postoperative pelvic WF of patients with muscle-invasive bladder cancer who received a radical cystectomy was incubated with bladder cancer cells with different EZH2 expression levels." (PMID 28968986, 2017). "In this study, we investigated the effects of EZH2 on drug resistance of bladder cancer cells, which could serve as a reference for the future application of inhibitors targeting EZH2 in bladder cancer." (PMID 28968986, 2017). "MiR-144 also reported to activate Wnt signaling in bladder cancer via targeting EZH2." (PMID 29163798, 2017). "Thus, many HOTAIR effects depend on EZH2, which is strongly upregulated both in breast and bladder cancers." (PMID 25994132, 2015). "Our results, using bladder cancer cell lines, extend this observation by showing that EZH2 expression may also lead to miR-200 family repression." (PMID 26517683, 2015). "The polycomb group gene, EZH2, is highly expressed in advanced bladder cancer." (PMID 25431950, 2014). "An increase of EZH2 expression in prostate and glioma cancers compared to normal tissue and a strong correlation between EZH2 level and bladder cancer stages may suggest that Polycomb group could partially control gene silencing observed in these tumors." (PMID 24709797, 2013). "ARID1A‐mutated bladder cancer cells exhibit sensitivity to PI3K inhibitors; thus combining EZH2 inhibitors with PI3K inhibitors can yield a synergistic anti‐tumour effect, consequently, ARID1A mutated bladder cancer may be treated with EZH2 and/or PI3K inhibitors." (PMID 39779467, 2025). "Moreover, at an optimal cut-off value of 8.23 ng/ml, EZH2 could effectively distinguish bladder cancer patients from healthy individuals, with an AUC of 0.87 (95% CI: 0.526–0.963, p < 0.0001), a sensitivity of 81.31%, and a specificity of 78.42%." (PMID 38476362, 2024). "Therefore, targeting SIRT7 and EZH2 could be a viable approach to enhancing CDDP efficacy in bladder cancer treatment." (PMID 39719443, 2024).
bladder cancer (continued). "It has also been implicated in bladder cancer, with one study finding a correlation between EZH2 overexpression and non-muscle invasive bladder cancer (NMIBC) in both mouse models and humans, as well as an increased likelihood of disease recurrence in those with EZH2 overexpression." (PMID 36980741, 2023). "Additionally, BRD4 has been shown to regulate EZH2 expression in bladder cancer." (PMID 38001678, 2023). "Thus, at these concentrations, GSK-126 could efficiently inhibit EZH2-dependent histone methylation, but only ARID1Amut bladder cancer cells were sensitive while ARID1Awt cells were resistant." (PMID 35852858, 2022). "Indeed, we also found an inverse correlation of EZH2 (eg. decreased expression upon EZH2 knock down and increased expression upon EZH2 overexpression) and the expression of miR-221, which facilitates EMT in bladder cancer and miR-222, which is associated with poor outcome in BC patients." (PMID 26517683, 2015). "Finally, to monitor whether the EZH2 activity is required for miR-200 repression, we carried out a pharmacological EZH2 inhibition using DZNep in three different bladder cancer cell lines." (PMID 26517683, 2015). "In addition, studies in HCCs and bladder cancers have demonstrated that miR-101 is epigenetically repressed by EZH2-mediated histone modification, which may also lead to the aberrant regulation of AP-1 signaling by miR-101." (PMID 25260594, 2014). "Their study found that during bladder cancer recurrence, CSC subpopulations become enriched, and EZH2 expression is elevated." (PMID 40635786, 2025). "Immunohistochemistry (IHC) and Western Blot (WB) analyses were used to assess the expression levels of SIRT7/EZH2 and RND3 in bladder cancer tissues, normal ureteral epithelial cells, and bladder cancer cell lines." (PMID 39719443, 2024). "In bladder cancer cells, TUG1 possesses direct miRNA interaction capability and can regulate the EZH2 expression level." (PMID 38256203, 2024). "Overall, in the promoter region of the RND3 gene, SIRT7 upregulated H3K27me3 and EZH2 downregulated H3K18ac, leading to a decline in RND3 expression and CDDP sensitivity in bladder cancer cells." (PMID 39719443, 2024). "Wu has recently reported that BRD4 can positively regulate EZH2 gene expression through upregulation of c-MYC and that the BRD4/c-MYC/EZH2 axis plays a vital role in the regulation of bladder cancer progression." (PMID 36733715, 2023). "For example, in bladder cancer cells, MINCR regulates the expression of EZH2 through miR-26a-5p, while silencing MINCR decreases cell proliferation and invasion and increases apoptosis." (PMID 35632705, 2022). "Although the exact regulatory effect of EZH2 on immune CPIs therapy remains unclear, EZH2 inhibitors in combination with immunotherapy seem to be promising antitumor treatment strategies due to their synergistic effects in PCa mouse models, and in head and neck and bladder cancer studies." (PMID 36135315, 2022). "In literature, correlation between elevated EZH2, SUZ12 and/or EED gene expression and poor prognosis of bladder carcinoma were reported." (PMID 36428492, 2022). "Inhibition of EZH2 by the small molecule inhibitor, UNC1999, suppresses bladder cancer cell growth and metastasis." (PMID 35409271, 2022). "Mechanistically, NRON stimulates EZH2 signaling to provide EMT induction and bladder cancer migration." (PMID 35236381, 2022). "In this way, SNHG1 enhances EZH2 expression in the nucleus to down-regulate CDH1, resulting in a decrease in E-cadherin levels and promoting metastasis and migration of bladder cancer cells." (PMID 35236381, 2022). "For the remaining tumors with SWI/SNF mutations, EZH2 inhibition with and without cisplatin might represent an effective option, as it has been recently demonstrated in bladder cancer cells and xenografts, through a mechanism that activates a natural killer (NK) cell-based immune response." (PMID 33397444, 2021).
bladder cancer (continued). "Pharmacological inhibition of EZH2 also inhibits tumor growth and improves the efficacy of anti-CTLA-4 treatment in bladder cancer." (PMID 34737746, 2021). "MYC, EZH2 and SOX9 are known to be repressed in response to BET inhibition in several malignancies, such as medulloblastoma, bladder cancer and myelofibrosis, but as yet the effect of JQ1 on these genes in TNBC has not been explored." (PMID 32166583, 2020). "BRD4 has been shown to be activated in bladder cancer, where it promotes tumor progression, BRD4 knockdown negatively regulated EZH2 transcription through downregulation of C-MYC and exerted anticancer effects." (PMID 32303673, 2020). "For example, CBX7 that inversely correlated with the tumor stage and grade progression in BC, or EZH2 expression that showed a significant increase in UCC specimens and bladder cancer cell lines." (PMID 30072631, 2018). "Specifically, T24 bladder cancer cells with EZH2 knockdown showed increased sensitivities to gemcitabine and DDP in the GC chemotherapy regimen, whereas bladder cancer cells with EZH2 overexpression showed significantly lower sensitivities to these drugs." (PMID 28968986, 2017). "In a second example, H19 represses gene expression through the interaction with enhancer of zeste homolog 2 (EZH2), a H3K27 methyltransferase in a part of the polycomb repressive complex 2 (PRC2) in bladder cancer." (PMID 28933364, 2017). "EZH2 is the H3K27 methyltransferase, which is overexpressed in various cancer types, including bladder cancer." (PMID 26484567, 2015). "SNF5 is antagonistic to EZH2, and EZH2 inhibitors may enhance the sensitivity of low‐expressing SNF5 bladder cancer cells to cisplatin." (PMID 39779467, 2025). "Few clinical trials have been conducted using EZH2 inhibitors in bladder cancer, and the single completed trial has not reported results (NCT03525795)." (PMID 36980741, 2023). "In bladder cancer cells, lncRNA SPRY4-IT1 could directly interact with miR-101 acting as a miRNA sponge, and miR-101 inhibition leads to increased EZH2 expression." (PMID 36497343, 2022). "Small molecule inhibitors of EZH2 (a H3K27 methyltransferase) have antimyeloma effects, and inhibitors of G9a (a H3K9 dimethyltransferase, also called EHMT2) have anticancer effects against urinary bladder cancer cells." (PMID 35409271, 2022). "In bladder cancer, USP21 is highly expressed and patients with high expression levels have poor survival, and USP21 can accelerate the proliferation and metastasis of bladder cancer cells via inhibiting EZH2 ubiquitination." (PMID 33791299, 2021). "In bladder cancer, SPRY4-IT1 mediates EZH2 expression by acting as an miR-101b sponge." (PMID 31092700, 2019). "ARID1A-depletion did neither increase EZH2 protein or trimethylated H3K27 levels in vitro nor did ARID1A expression correlate with EZH2 or H3K27me3 amounts in human bladder carcinomas." (PMID 30138427, 2018). "In accordance with the in vitro data, we did not observe differential EZH2 mRNA amounts comparing bladder carcinomas of the TCGA 2017 data set either showing high ARID1A mRNA levels or low ARID1A mRNA expression." (PMID 30138427, 2018). "Secondly, regardless of the EZH2 expression status of T24 bladder cancer cells, incubation with pelvic WF obtained after radical cystectomy in muscle-invasive bladder cancer induced chemotherapy drug resistance in the cells." (PMID 28968986, 2017). "In addition, a biologically active biphenolic compound, honokiol was isolated from Magnolia officinalis that inhibited human urinary bladder cancer (UBC) cell proliferation, migration and invasion by downregulating EZH2." (PMID 28410242, 2017). "Specifically, EZH2 mediates the role of the MALAT1–PRC2 partnership in the epithelial–mesenchymal transition in renal cell carcinoma, whereas SUZ12 promotes the role of the MALAT1-PRC2 binding in tumor metastasis in bladder cancer." (PMID 27998273, 2016).